FGFR1OP2 (FGFR1 oncogene partner 2)
Description:
May be involved in wound healing pathway.
Synonyms: DKFZp564O1863; HSPC123-like; WIT3.0
Tractability: PROTAC: ubiquitination databases record sites on it; its protein half-life has been measured.
Gene: Protein-coding gene on chromosome 12 (26,938,401 to 26,966,650, forward strand). Ensembl gene ENSG00000111790.
Subcellular location: Cytoplasm
Subcellular location (Human Protein Atlas): Mitochondria
Pathways (Reactome):
Disease: Signaling by FGFR1 in disease; Signaling by cytosolic FGFR1 fusion mutants
Gene Ontology:
Molecular function: protein binding; identical protein binding
Biological process: response to wounding
Cellular component: cytosol; cytoplasm
Genetic constraint (gnomAD): Loss-of-function variants: 11 observed, 22.11 expected, observed/expected ratio (o/e) 0.5, 90% interval 0.31 to 0.82. The upper end of that interval is the gene's LOEUF score, 0.82, which puts it in group 3 of 6, group 1 being the genes least tolerant of losing a copy. Missense variants: 179 observed, 235.21 expected, observed/expected ratio (o/e) 0.76, 90% interval 0.67 to 0.86. Synonymous variants: 76 observed, 81.61 expected, observed/expected ratio (o/e) 0.93, 90% interval 0.77 to 1.13.
Homologues: Orthologues: chimpanzee FGFR1OP2 (100% identical), macaque FGFR1OP2 (100% identical), rabbit FGFR1OP2 (99% identical), rat Fgfr1op2 (99% identical), pig FGFR1OP2 (98% identical), dog FGFR1OP2 (98% identical), guinea pig FGFR1OP2 (92% identical), mouse Fgfr1op2 (85% identical), tropical clawed frog fgfr1op2 (72% identical), zebrafish fgfr1op2 (65% identical), Drosophila melanogaster Fgop2 (27% identical), Caenorhabditis elegans C14B1.8 (17% identical). Paralogues in human: SIKE1 (42% identical).
Diseases named in the same sentence as FGFR1OP2 in open-access papers:
FGFR1OP2 is named in the same sentence as 9 diseases in open-access papers, as found by Europe PMC text mining. Sharing a sentence is not in itself a finding about the gene and the disease. The quoted sentences say what the papers report.
ovarian carcinoma (2 papers, 2017 to 2024). A malignant neoplasm originating from the surface ovarian epithelium. "In the present study, RPL23, FGFR1OP2, CAPN10, ALDH1L1 and ACSM1 were significantly downregulated in ovarian cancer, while the up-regulation of RPL23, FGFR1OP2, CAPN10 and ALDH1L1 was associated with poor prognosis in patients with ovarian cancer." (PMID 39478854, 2024). "The top predicted CNV regions associated with risk included FGFR1OP2 (RR=0.20, P=5 × 10−4) and PABPC4L (RR=0.22, P=0.006) for breast and ovarian cancer, respectively." (PMID 28145423, 2017). "PKM2, MRPS12, NDUFC2, HPDL, MRPL14, COA6 and RNF144B were significantly upregulated in ovarian cancer tissues than in normal tissues (P < 0.05), while RPL23, FGFR1OP2, CAPN10, ALDH1L1 and ACSM1 were significantly down-regulated (P < 0.05)." (PMID 39478854, 2024).
acute myeloid leukemia (1 paper, 2020). Acute myeloid leukemia (AML) is a group of neoplasms arising from precursor cells committed to the myeloid cell-line differentiation. "Interestingly, FGFR1OP2 has been extensively investigated in the context of hematopoietic malignancies including acute myeloid leukemia and myelomonocytic leukemia where it is involved in monocyte precursor differentiation in the bone marrow." (PMID 34968236, 2020).
Atrophy (1 paper, 2011). Any weakening or degeneration, especially through lack of use. "However, FGFR1OP2/wit3.0 may provide a novel clue to understanding the pathological mechanism of post-dental extraction atrophy of jawbone leading to the targeted preventive and therapeutic modalities." (PMID 21283824, 2011).
metastatic disease (1 paper, 2024). "The remaining 2 candidate genes in the genetically defined region, Fgfr1op2, and Slco1a5, have not yet been evaluated for their role in metastatic disease." (PMID 38722825, 2024).
tumor (2 papers, 2021 to 2024). "We confirmed an aberrant increase of cassette exon skipping in tumor specimens for PACSIN2 exon 8, DIAPH1 exon 2, FGFR1OP2 exon 4, MARK3 exon 16, DST exon 93, LMO7 exon 10, and RBM5 exon 7, whereas ADD3 exon 13, MAP3K7 exon 12, and MARK2 exon 15 were preferentially included in tumor specimens." (PMID 34202984, 2021).
FGFR1OP2 also shares sentences with these, for which no sentence is quoted: breast carcinoma (2 papers); breast tumor (1); cancer (1); lung adenocarcinoma (1).